XBP1 (X-box binding protein 1)
Diseases named in the same sentence as XBP1 in open-access papers (continued):
Sharing a sentence is not in itself a finding about the gene and the disease.
tumor (continued). "In addition to the role of IRE1α-XBP1 in the suppressive function of tumor-infiltrating myeloid cells, recent studies have demonstrated a major function for the UPR downstream target CHOP as a key regulator of MDSC activity and turnover in tumors." (PMID 28105371, 2017). "In addition, doxorubicin significantly inhibited XBP1 activation in CD138+ tumor cells isolated from MM patients." (PMID 27634301, 2016). "Similarly, decreases of other UPR mediators; XBP1, IRE1 and PERK, through knock-downs, knock-outs and null mutations in a range of cancer models result in decreased tumour size and reduced angiogenesis." (PMID 26927180, 2016). "Overall, our data demonstrate that iNOS inhibition could impair EMT and tumor cell migration by impairing ER stress (IRE1α/XBP1) and the crosstalk between ATF4, ATF3, and TGFβ." (PMID 25849745, 2015). "However, there was a significant correlation of XBP1 expression with clinical stage (p < 0.01), degree of malignancy (p < 0.05), and tumor necrosis rate (p < 0.05)." (PMID 26633383, 2015). "Therefore, it will be important to determine the extent of this XBP1-HIF-1α co-regulation among the subsets of TNBCs as well as cancer stem cells from other tumor types." (PMID 25927911, 2014). "In addition, quinotrierixin inhibits tumor cell growth, and the inhibitory effects of quinotrierixin and other triene-ansamycin group compounds on tumor cell growth are highly correlated with their effects against XBP1 activation in tumor cells." (PMID 23335849, 2013). "When the spliced variant of XBP1 was expressed in IRE1α dominant-negative expressing cells angiogenesis was restored, suggesting that signaling through the IRE1α-XBP1 arm of the UPR is essential for angiogenesis in the early stage of tumor development." (PMID 22934019, 2012). "In addition to this study, two independent reports have also demonstrated a role for XBP-1 in tumor establishment, growth and angiogenesis." (PMID 20824063, 2010). "However, the expression profiles of K14-cre;ApcCKO/+ acinar tumors also included a human luminal tumor-defining gene, XBP1 and stained positive for K8." (PMID 19197353, 2009). "However, it should be noted that two human luminal tumor-defining genes (XBP1 and GATA3, were both highly expressed in murine luminal tumors." (PMID 17493263, 2007). "A cluster enriched for genes associated with the luminal/ER+ tumor subtypes (N-acetyltransferase 1, estrogen receptor 1, putative G-protein-coupled receptor, trefoil factor 3, GATA binding protein 3, and X-box binding protein 1) was also present in this gene set." (PMID 17150101, 2006). "The role of FN1 in tissue stem cells with high communication intensity may facilitate interactions with other cells in the tumour microenvironment by supporting tumour cell attachment and spread, suggesting that XBP1, TRPC6 and TTC28 may influence the tumour microenvironment." (PMID 40046334, 2025). "Notably, the levels of p-STAT3 and total STAT3 were significantly reduced in KPC tumor-bearing Xbp1mKO mice compared to corresponding Xbp1fl/fl mice suggesting that the IRE1α/XBP1 signaling mediates the activation of the JAK-STAT signaling in skeletal muscle of KPC tumor-bearing mice." (PMID 40655023, 2025). "The mechanisms by which ERS affects tumor-associated DCs have also been elucidated, where changes in the TME leading to the accumulation of unfolded protein induce the activation of ERS and IRE1α–XBP1 signaling, thereby inhibiting their antigen-presenting function." (PMID 39080273, 2024). "Also, tapbp mRNA, a reported RIDD target in splenic cDC1s is not found as DEG in XBP1 deficient tumor cDC1s." (PMID 37346037, 2023).
tumor (continued). "And XBP1, as a transcription factor, promoted the transcription of immunosuppressive molecules such as PD-1, TIM-3, and LAG-3 in CD8+ T cells, thereby causing CD8+ T cells to exhibit a functionally depleted and immunosuppressive state and promoting tumor progression." (PMID 37801479, 2023). "IRE1α could also regulate the expression and secretion of cytokines via XBP1 to promote tumor cell survival under ER stress, especially tumor-promoting factors like TNFα, IL-8, and VEGFα.40,41 Therefore, we wondered whether SIRT7 also regulated these cytokines with oncogenic function." (PMID 36918544, 2023). "Moreover IRE1α-XBP1 is also thought to mediate angiogenic factors in the tumor cells themselves, indicating that the IRE1α/XBP1 axis may be crucial for mediating angiogenesis in both cancer cells and TAMs." (PMID 37067519, 2023). "Overall, E2 levels were significantly positively correlated with tumor enrichment in the hallmark estrogen response pathway (red bars) and with the expression of genes demonstrated to be transcriptionally regulated by ER (BCL2, IGF1R, GATA3, PIK3CA) and ligand-dependent ER (ESR1, XBP1, TFF1)." (PMID 36428742, 2022). "Furthermore, XBP1-s can also promote tumor development by modulating immune cells." (PMID 35269888, 2022). "Secondly, our result showed that XBP1 expression was higher in chemotherapy-sensitive cases and that XBP1 was an independent predictive factor for NAC response in BC patients treated with NAC, suggesting XBP1 may regulate chemotherapeutic response to inhibit tumours." (PMID 35543228, 2022). "Another study reported that tumor-derived factors trigger lipid peroxidation in tumor-associated DCs (TADCs), thereby activating inositol-requiring protein 1α (IRE-1α) and its target X-box-binding protein 1 (XBP1) -mediated endoplasmic reticulum stress response." (PMID 36456877, 2022). "In this review, we will outline the structural and functional differences between XBP1-u and XBP1-s, as well as their physiological and pathological functions, especially in the regulation of metabolism, differentiation, inflammation, neurodegenerative diseases, and tumor progression." (PMID 35269888, 2022). "In addition, our results indicate that hypoxia could cause to the cascade of reactions, leading to the increased expression of XBP1 and accelerated tumor growth." (PMID 34093792, 2021). "Therefore, it will be important, in future studies, to evaluate the consequence of IRE1alpha/XBP1 axis inhibition on the cross-talk between PEL cells and cells of the tumor environment or whether IRE-XBP1 signaling inhibition may interfere with HIF1α." (PMID 33513694, 2021). "Moreover, toyocamycin suppressed the constitutive activation of XBP1 expression in MM cell lines, inhibited tumor growth in a MM xenograft in vivo model, and synergistically enhanced the chemotherapeutic effect of bortezomib in MM cells, including the bortezomib-resistant ones." (PMID 33562589, 2021). "Unfolded protein response (UPR) played an important role in determining the fate of tumor cells when undergoing ER stress, which induced apoptosis by upregulation of p-eIF2-α expression and promoted cell survival by activating inositol-requiring kinase to increase XBP1 expression 35-37." (PMID 32724476, 2020). "Thus, XBP1 acts as an essential survival factor for hypoxic stress and tumor growth." (PMID 30754624, 2019). "Therefore, proper regulation of XBP1 expression is important for tumor suppression." (PMID 30783083, 2019). "Prostatosphere growth of these cell lines, an indication of stemness, was also markedly inhibited in the presence of MKC8866, which was consistent with IRE1α or XBP1 knockdown experiments, suggesting that IRE1α may be involved in mechanisms of tumor initiation in PCa." (PMID 30679434, 2019). "Thus, IRE1/XBP1 inhibitors may represent a feasible strategy for tumor therapy, while PERK inhibitors may vanish the goal." (PMID 29531800, 2018).
tumor (continued). "Indeed, it is likely that in XBP1+/RIDD− tumors, inhibition of IRE1 RNase with small molecules or selective inhibition of the XBP1 mRNA ligase RtcB might lead to significant impairment of tumor growth." (PMID 29311133, 2018). "In contrast, Xbp1-deficient IECs exhibit increased turnover through NFκB-dependent activation of STAT3, promoting colitis-associated cancer and spontaneous adenomatous polyposis coli (APC)-related tumors in mice, suggesting that XBP1 might act as a tumor suppressor in the intestine." (PMID 28860159, 2017). "Consistent with the immunogenic effects induced upon deleting or silencing Xbp1 in tDCs, targeting lipid uptake or inhibiting key mediators of fatty acid oxidation has been shown to boost anti-cancer immunity by enhancing myeloid cell function in the tumor microenvironment." (PMID 28105371, 2017). "The biological effects of the different mutations on tumor progression are at present not clear; however, a number of the IRE1α mutations identified in human cancers appear to provide a survival advantage that can still splice XBP1, but cannot induce RIDD." (PMID 27303918, 2016). "This suggests that quinotrierixin may suppress tumor cell growth by inhibiting XBP1." (PMID 23335849, 2013). "Aberrant activation of the UPR sensors (IRE1α-XBP1, PERK-ATF4, ATF6) and their downstream signaling pathways have emerged as critical regulators of tumor angiogenesis, metastasis, and response to chemotherapy, targeted therapy, and immunotherapy." (PMID 40745648, 2025). "In the spatial transcriptomic application, we observe negative partial correlations in the normal region and positive partial correlations in the tumor region for the gene pairs THBS2-COL12A1 and XBP1-SPINT2." (PMID 39954675, 2025). "Our results in the present study demonstrate that targeted ablation of XBP1 significantly reduced fatty acid oxidation and gene expression of various molecules involved in fatty acid metabolism in the skeletal muscle of KPC tumor-bearing mice." (PMID 40655023, 2025). "Under ER stress, PRKCSH-expressing tumor cells (PRKCSH [+]) exhibit moderate activation of the IRE1α–XBP1–JNK pathway and secrete IL-6 and IL-8, promoting tumor survival and supporting M2 macrophage polarization." (PMID 41350724, 2025). "The IRE1α/XBP1 signaling also activates the IL6-JAK-STAT3 signaling and fatty acid metabolism in skeletal muscle of KPC tumor-bearing mice." (PMID 40655023, 2025). "In tumor cells, activation of key UPR molecules such as the IRE1α/XBP1 and PERK/ATF4 pathways promotes the formation of an immunosuppressive TME." (PMID 41407677, 2025). "Muscle-specific deletion of XBP1 is sufficient to improve skeletal muscle mass and strength in KPC tumor-bearing mice." (PMID 40655023, 2025). "Muscle-specific ablation of XBP1 inhibits the activation of proteolytic systems and muscle wasting in KPC tumor-bearing mice." (PMID 40655023, 2025). "We observe negative partial correlations in the normal region and positive partial correlations in the tumor region for gene pairs THBS2-COL12A1 and XBP1-SPINT2 and the inverse partial correlation pattern for ERGIC3-FN1." (PMID 39954675, 2025). "This pro-tumorigenic polarization is further reinforced by changes in lipid composition; IRE1α-XBP1 and IRE1α-STAT3 are both simultaneously activated to ensure TAM survival in favor of the tumor." (PMID 41301006, 2025). "Altogether, these results suggest that targeted ablation of XBP1 reduces fatty acid oxidation and oxidative stress in skeletal muscle of KPC tumor-bearing mice." (PMID 40655023, 2025). "Tumor tissues also showed a significant upregulation of XBP1s, the spliced form of XBP1, indicating an activated unfolded protein response (UPR) within the tumor microenvironment." (PMID 41350724, 2025). "This ligand-independent event occurs upon IRE1/XBP1 downregulation and concomitant JNK activity attenuation, highlighting the tumor-suppressive aspect of UPR in MM cells." (PMID 40563622, 2025).
tumor (continued). "Heatmap analysis of DEGs showed that gene expression of several molecules, especially those involved in the IRE1α/XBP1 arm of the UPR, was highly upregulated in GA muscle of KPC tumor-bearing mice compared to control mice." (PMID 40655023, 2025). "Intriguingly, our RNA-Seq analysis demonstrates that XBP1 regulates the gene expression of multiple components of this pathway, including cell surface receptors for IL-6 in cachectic muscle of KPC tumor-bearing mice." (PMID 40655023, 2025). "Mechanistically, emerging epigenetic regulators like the LINC00963/miR-320a/XBP1 axis and ZNF263-mediated super-enhancer activation provide novel molecular insights into tumor heterogeneity and targeted intervention." (PMID 41407677, 2025). "IHC images of tumor slices showed that the shIGFBP1 group exhibited higher expression of CHOP, GRP78, XBP1." (PMID 38700505, 2024). "It is established that chronic ER stress can reduce T cell function by inhibiting the oxidative metabolism in T cells via XBP1 or decreasing T-bet expression via PERK, ATF4 and Chop in tumor-infiltrating CD8+ T cells." (PMID 39408714, 2024). "Studies have suggested that XBP1, a downstream molecule of the IRE1 pathway, can facilitate tumor angiogenesis independently of VEGF." (PMID 39080273, 2024). "More importantly, tumor tissues enriched with cholesterol in tumor-infiltrating CD8+T cells induced prominent ER stress and consequently XBP1-dependent transcription of PD-1 and 2B4, leading to the exhaustion of CD8+T cells and impaired anti-tumor immunity." (PMID 38291473, 2024). "Studies have demonstrated that XBP1-mediated expression of T-cell-suppressive checkpoints in myeloid cells, such as PD1, prevents the activation of tumour infiltrating T cells in GBM, thereby leading to resistance to anti-PD1 therapy." (PMID 38297380, 2024). "Cholesterol is notably enriched in tumor tissues and its accumulation in tumor‐infiltrating CD8+ T cells results in the upregulation of T cell exhaustion markers and an ER‐stress‐XBP1‐dependent inhibition of anti‐tumor function." (PMID 38922759, 2024). "XBP‐1 splicing (s‐XBP1) was significantly lower in both the skeletal (−26.14%, p = 0.067) and cardiac (−42.44%, p = 0.005) muscles of tumor‐bearing rats." (PMID 39294861, 2024). "Aberrant activation of IRE1α-XBP1 influences T cell differentiation in the tumor microenvironment (TME), consequently promoting tumor cell expression." (PMID 39062458, 2024). "In X-box binding protein 1 (XBP1)-luciferase transgenic mice, variations in UPR reflected different metabolic and hypoxic microenvironment and predicted tumor growth." (PMID 38700505, 2024). "Among the main responses of UPR, the IRE1α-XBP1 and PERK/eIF2α/ATF4 pathways play critical roles in TNBC, such as tumor initiation, vascularization, progression, and tumor microenvironment reprogramming." (PMID 37540709, 2023). "It is worth mentioning that when we investigated the impact on stressing tumor cells by each component alone or combined, i.e., DSF, Cu, DFS/Cu, IR, DSF/Cu+IR, we found DSF/Cu+IR is most effective in activating the XBP1 axis, a crucial parameter of ER stress." (PMID 37714830, 2023). "Currently, XBP1 is a critical regulator of UPR under ER stress, and is a key drug target in tumor development, especially in Myc-driven cancers." (PMID 37008067, 2023). "In contrast, tumor cDC1s from XBP1ΔDC mice showed signs of IRE1 hyperactivation, as indicated by higher expression of the Xbp1 spliced over the unspliced form." (PMID 37346037, 2023). "Mechanistically, SIRT7 selectively activated the IRE1α-XBP1 axis to potentiate the pro-survival ERK signal pathway and the secretion of tumor-promoting cytokines like IL-8, TNF-α and VEGFA." (PMID 36918544, 2023). "Mechanistically, SIRT7 selectively activated the IRE1α-XBP1 axis to potentiate the pro-survival ERK signal pathway and the secretion of tumor-promoting cytokines." (PMID 36918544, 2023).
tumor (continued). "Therefore, it can be proposed that NF-κB p65 might also indirectly promote PD-L1 expression via SIRT7 and its-mediated IRE1α-XBP1 axis, and this speculation might provide more evidence supporting the role of NF-κB p65 in anti-tumor immunity, which needs more investigation in the future." (PMID 36918544, 2023). "The expression level of these genes differs significantly between the tumor and normal tissues, but CREB3L3 and TRIB3, and XBP1 are overexpressed, while PPP1R15A is expressed conversely." (PMID 37880674, 2023). "In TNBC, BHLHE41/DEC2 is a crucial tumor-suppressing molecule, since it can inhibit HIF-1 and possibly XBP1 functions and cancer stem cells." (PMID 37511489, 2023). "Inhibition of IRE1α-XBP1 activation can restore the OXPHOS and anti-tumor immunity against ovarian tumor." (PMID 36147929, 2022). "Expression of XBP1 drives TAM in a pro-tumourigenic direction, thus providing a survival advantage to the tumour." (PMID 35711841, 2022). "TFs, such as XBP1, TAF7, ELF3, MYC, MAX, etc., were more enriched in tumor cells of luminal BC than the other two subtypes." (PMID 36077333, 2022). "Tumor immune cells (PTPRC/CD45+) also consisted of B cells (MS4A1/CD20+), plasma cells (XBP1+), macrophages (CD14+), dendritic cells (CD80+, CD86+), and mast cells (TPSAB1+)." (PMID 35742914, 2022). "We found that XBP1, TAF7, ELF3, MYC, MAX, etc., were more enriched in tumor cells of luminal BC than the other two subtypes." (PMID 36077333, 2022). "Increased XBP1-s promotes glycolysis by positively regulating the expression of hexokinase 2 (HK2) and enhances tumor cell viability under hypoxia." (PMID 35269888, 2022). "Although there are many markers to assess hypoxia in tumours, such as HIF-1α, X-Box Binding Protein 1 (XBP1), GLUT1 and Vascular endothelial growth factor (VEGF), the results however have been conflicting in various studies." (PMID 35659359, 2022). "As an alternative splicing transcription factor in the regulation of the UPR during ERS, X-box binding protein 1 (XBP1) is commonly expressed in various tumors and closely related to tumorigenesis and tumor progression." (PMID 36092910, 2022). "We demonstrated a novel mechanism of tumor invasion and metastasis in NSCLC that involves the activation of the XBP1/IGFBP3/MMP-9 pathway." (PMID 34094948, 2021). "The transcription factor JUN was reported to activate the transcription of the promoters of several key UPR effectors, such as XBP1 and ATF4, to inhibit tumour cell apoptosis." (PMID 33971902, 2021). "X-box binding protein 1 (XBP-1) is an important transcription factor in the UPR pathway, which has been reported to accelerate tumor growth by inhibiting apoptosis." (PMID 34521445, 2021). "Knocking down XBP1, CXCR4, and CD44 by siRNA technology altered the interplay between tumor cells and HBMECs." (PMID 34093792, 2021). "Targeting XBP1 inhibits the ability of pro-tumor cytokines, such as IL-6 and VEGFA, as well as promotes tumor growth and metastasis." (PMID 34667145, 2021). "TAMs enhanced tumor growth of the subcutaneously injected luciferase tumor cells (CT26-luciferase) in NOD/SCID mice, while knockout of XBP1 in miTAMs inhibited tumor growth." (PMID 34667145, 2021). "Given the increased expression of XBP1, CXCR4, and CD44 during ERS/UPR activation under hypoxic condition in DLBCLs, we further investigated possible contribution of this pathway to the tumor APVT growth pattern." (PMID 34093792, 2021). "Differential expression levels of XBP1 are found in CRC cell lines and tumor tissues from a subset of CRC patients." (PMID 33746610, 2021). "Silencing XBP1 and CD44 reduced tumor cell invasion and adhesion to HBMECs, whereas silencing CXCR4 decreased the tumor cells migration." (PMID 34093792, 2021). "Ern1- or Xbp1-CKO macrophages enabled us to distinguish different roles within the IRE1α/XBP1 axis relative to immune dysregulation and tumor growth." (PMID 32520957, 2020).